PCSK9 (proprotein convertase subtilisin/kexin type 9)
Diseases named in the same sentence as PCSK9 in open-access papers (continued):
Sharing a sentence is not in itself a finding about the gene and the disease.
Hypercholesterolemia (continued). "Summing up, this small non-randomized study showed that PCSK9 inhibitors may affect hemostatic variables in subjects with isolated hypercholesterolemia." (PMID 35566668, 2022). "Another recent study with 25 patients suffering from familial hypercholesterolemia (mean baseline LDL-cholesterol: 201 mg/dL, mean baseline Lp(a): 69 mg/dL) also showed amelioration of endothelial function in response to 12 weeks of treatment with PCSK9-antibodies." (PMID 35052831, 2022). "Furthermore, treatment with PCSK9 inhibitors in a cohort of 26 patients with familial hypercholesterolemia, where statins and ezetimibe did not efficiently reduce LDL cholesterol, improved hepatic steatosis in those patients with a low triglyceride/HDL ratio." (PMID 35162992, 2022). "Congruently, pharmacological inhibition of PCSK9 with evolucumab reduced the increase in CIMT along the time in patients treated with statin and improved the vascular functionality as determined by carotid stiffness in patients with familial hypercholesterolemia." (PMID 36294964, 2022). "This narrative review aims to discuss the place in therapy of ezetimibe, PCSK9 inhibitors, BDA, and inclisiran and describe their relative pharmacokinetic (PK) profiles, efficacy and safety as monotherapy and combination therapy, and cardiovascular benefit(s) when used for hypercholesterolemia." (PMID 34869702, 2021). "This narrative review aims to discuss the place in therapy of ezetimibe, PCSK9 inhibitors, BDA, and inclisiran and describe their relative pharmacokinetic (PK) profiles, efficacy and safety as monotherapy and combination therapy, and CV benefit(s) when used for hypercholesterolemia." (PMID 34869702, 2021). "PCSK9 inhibition by CBE is actively attributed to icaritin, and the use of CBE and icaritin could be an alternative therapeutic approach in the treatment of hypercholesterolemia." (PMID 33673187, 2021). "Two fully human anti-PCSK9 monoclonal antibodies (MAbs), alirocumab (SAR236553/REGN727 from Regeneron Pharmaceuticals/Sanofi) and evolocumab (AMG145 by Amgen), are currently approved for the treatment of hypercholesterolemia by the US Food and Drug Administration and European Medicines Agency." (PMID 30761308, 2018). "In the present report, increase in LDL fraction due to altered PCSK9 level or hypercholesterolemia (independent of PCSK9 signaling) would increase the probability of sorafenib binding to LDL, thus reducing the fraction of drug available for uptake by the tumor cells." (PMID 30386595, 2018). "Consequently, PCSK9 inhibition is an emerging pharmacological target for patients with familial hypercholesterolemia and/or high levels of LDL-C who do not achieve sufficient lipid lowering with statin therapy." (PMID 25136459, 2014).
Hypercholesterolemia (continued). "Furthermore, in T2D patients with hypercholesterolemia, PCSK9 levels may not be affected by ezetimibe or its combination with statins." (PMID 39951410, 2025). "In the treatment setting, PCSK9 inhibitor antibodies may find a useful place as part of the existing guideline recommendations for the treatment of hypercholesterolemia in patients with or without clinical ASCVD needing additional LDL-C reductions despite statin regimens." (PMID 35795514, 2022). "Taken together with the marked reductions in plasma cholesterol associated with genetic or therapy-induced reductions in plasma PCSK9, our findings raise the possibility that SURF4 could represent an additional novel therapeutic target for the treatment of hypercholesterolemia." (PMID 30251625, 2018). "We therefore evaluated the effect of PCSK9-inhibition on lipoprotein subfractions in patients with FDBL and compared it to the effect in patients with LDL-hypercholesterolemia and patients with mixed hyperlipidemia (not FDBL)." (PMID 35320320, 2022). "Hence, PCSK9 inhibitors may manage hypercholesterolemia without disturbing glucose metabolism." (PMID 35571202, 2022). "In this way, both statins and PCSK9 inhibitors are valuable adjuncts to the overall antithrombotic armamentarium in hospitalized hypercholesterolemic COVID-19 patients, particularly in COVID-19 patients with severe hypercholesterolemia—whether or not they have the diagnosis of HeFH." (PMID 34722654, 2021). "The depletion of circulating PCSK9 lowered LDL levels in transplanted mice, however, failed to effectively treat hypercholesterolemia under high-fat diet." (PMID 34731223, 2021). "The remaining 30 parameters were calibrated on the basis of plasma PCSK9, LDL-C, HDL-C, and Lp(a) study-level data in healthy and hypercholesterolemia subjects using a nonlinear fixed-effects modeling technique." (PMID 31292220, 2019). "Patients with familial hypercholesterolemia (FH) have reduced or absent LDL receptors and should therefore have elevated PCSK9 levels." (PMID 23537802, 2013). "Notably, proprotein convertase subtilisin/kexin type 9 (PCSK9) inhibitors are endorsed as adjuncts to maximally tolerated statin therapy for patients with CKD and familial hypercholesterolemia or clinical ASCVD who do not achieve LDL-C targets." (PMID 41546841, 2026). "Since many familial hypercholesterolemia patients do not reach target LDL-C levels, other medication options are the addition of the cholesterol absorption inhibitor ezetimibe, bile acid sequestrants, and PCSK9-targeting monoclonal antibodies." (PMID 38668084, 2024).
Hypercholesterolemia (continued). "In contrast, elevated serum levels of LDL-C, HDL-C, APOA, APOB, Pure hypercholesterolaemia, as well as the use of lipid-lowering drugs such as HMGCR inhibitors and PCSK9 inhibitors, did not exhibit statistically significant associations with either an increased or decreased risk of urinary stones." (PMID 38107516, 2023). "The model demonstrates that in hypercholesterolemia subjects, a 50% decrease of LDL-C by inclisiran is achieved with a 10% lesser reduction in PCSK9, which could not be explained by differences in baseline levels alone." (PMID 31292220, 2019).
atherosclerosis (510 papers, 2007 to 2026). A disease characterized by the build-up of fatty material and calcium deposition in the arterial wall resulting in partial or complete occlusion of the arterial lumen. "Loss-of-function mutations in PCSK9 are clearly associated with naturally low cholesterol levels and atherosclerosis prevention." (PMID 40430848, 2025). "Another example of a unimodal antigeroid syndrome related to atherosclerosis comes from the discovery of low levels of LDL cholesterol associated with loss-of-function mutations at PCSK9 (including haploinsufficiency)." (PMID 39928272, 2025). "Outside the basic impact on liver LDLC uptake, PCSK9 is associated with the initiation, progression and complications of atherosclerosis such as vascular inflammation, platelet functions or thrombogenesis." (PMID 41002634, 2025). "This shows that PCSK9 has a role in hyperlipidemia and is linked to atherosclerosis, a chronic degenerative vascular disease." (PMID 40354375, 2025). "Here, we explored Nef's role in HIV-associated atherosclerosis using a novel model: HIV-infected humanized mice expressing a gain-of-function mutant of proprotein convertase subtilisin/kexin type 9 (PCSK9) and fed a high-fat diet." (PMID 40237461, 2025). "For example, RNA-based approaches silencing hepatic PCSK9 has been shown efficacy in reducing residual vascular risk, representing a novel strategy for managing lipid-driven atherosclerosis in high-risk populations." (PMID 41427047, 2025). "For example, the application of CRISPR has explored how effectively it can target and repair such genes as mutations of PCSK9, which in turn would reduce cholesterol levels along with the risk of atherosclerosis." (PMID 40662044, 2025). "Variants in the PCSK9 gene, known to increase LDL levels, have been linked to an increased risk of subclinical atherosclerosis, with elevated plasma PCSK9 levels directly correlated with LDL levels in patients undergoing PD." (PMID 39457689, 2024). "The expression levels of proteins associated with the lipid metabolism (LPA, APOB, and PCSK9) were associated with increased levels of atherosclerosis-promoting lipid indicators [Total Cholesterol, Low-density Lipoprotein (LDL)]." (PMID 38689297, 2024). "Recommended for patients with inherited high cholesterol or high risk of atherosclerosis, PCSK9 inhibitors help those with greater risk achieve their LDL-C targets." (PMID 39770423, 2024). "Available data indicates that lipid-associated proteins, including PCSK9, are associated with increased atherosclerosis-associated lipid markers (total cholesterol, LDL-C, APOB), which is consistent with our MR analysis results on cardiovascular risk factors." (PMID 38689297, 2024). "Atherosclerosis is a major cause of heart-related deaths worldwide, and researchers are focusing on PCSK9 due to its ability to lower cholesterol, even in individuals already taking statins." (PMID 39770423, 2024). "It suggested that PCSK9 modulates apoptosis-associated proteins to facilitate endothelial cell apoptosis, ultimately contributing to the development of atherosclerosis." (PMID 39767636, 2024). "Meanwhile, PCSK9 levels in plasma are linked with atherosclerosis development by lipid pathways as a promising biomarker in atherosclerosis." (PMID 39975967, 2024). "Regarding to the progression of carotid atherosclerotic stenosis, plasma PCSK9 levels are associated with 10‐year progression of atherosclerosis as evaluated by total plaque area in 643 Asian patients." (PMID 38402551, 2024).
atherosclerosis (continued). "It was initially believed that the role of PCSK9 in atherosclerosis was only linked to its involvement in LDLc metabolism." (PMID 38886277, 2024). "Using these preclinical models, recent research has explored mRNA vaccines intended to influence inflammatory processes implicated in atherosclerosis and to suppress PCSK9, which modulates LDL-C levels." (PMID 39712846, 2024). "Analysing the bibliometric landscape and global research trends associated with PCSK9 inhibitors can contribute valuable insights into comprehending atherosclerosis." (PMID 39247108, 2024). "We investigated the association between plasma PCSK9, measures of immune–inflammatory status and markers of atherosclerosis in 52 consecutive patients with primary Sjögren’s syndrome (pSS) in comparison to healthy controls (HCs)." (PMID 37759784, 2023). "PCSK9 inhibition attenuates atherosclerosis progression and lowers the risk for acute cardiovascular events." (PMID 36982171, 2023). "PCSK9 is closely associated with the indirect regulation of lipid metabolism and participates in the direct regulation of atherosclerosis via the accumulation of foam cells and inflammatory mediators as well as apoptosis in vascular walls." (PMID 36911736, 2023). "PCSK9 can be linked to many pathological conditions, such as insulin resistance, liver steatosis or atherosclerosis." (PMID 37004042, 2023). "It turned out that PCSK9 is associated with platelet activation in the development of atherosclerosis." (PMID 36831039, 2023). "Despite the success of statins and PCSK9 antibodies, atherosclerosis remains a major risk factor for cardiovascular disease." (PMID 36983007, 2023). "This enhancement ultimately reduces the formation of atherosclerotic plaques in adeno-associated virus-proprotein convertase subtilisin/kexin type 9 (AAV-PCSK9)-induced atherosclerosis in ACE10/10 mice." (PMID 37928535, 2023). "Studies so far have suggested that PCSK9 is associated with procoagulation, enhancing the development of atherosclerosis." (PMID 36768292, 2023). "Although Lp(a) is a known cause of atherosclerosis and cardiac valvular damage, until now, only mAbs-targeting PCSK9 and inclisiran have been found to reduce its levels quite modestly." (PMID 38203499, 2023). "We previously reported that mice with increased macrophage-specific angiotensin-converting enzyme, termed ACE10/10 mice, resist atherosclerosis in an adeno-associated virus-proprotein convertase subtilisin/kexin type 9 (AAV-PCSK9)-induced model." (PMID 37928535, 2023). "There is a significant positive correlation between plasma PCSK9 levels and the risk of atherosclerosis." (PMID 36970356, 2023). "As far as targeting PCSK9 is concerned, it is known to be safe because humans with null mutations in PCSK9 are asymptomatic except for the fact that they are resistant to atherosclerosis." (PMID 37373933, 2023). "Previous studies have shown that PCSK9 is positively correlated with some traditional risk factors for atherosclerosis, and our study also confirmed a significant positive correlation between PCSK9 and TC and LDL-C." (PMID 38115042, 2023). "It is a known fact that higher PCSK9 plasma levels have been linked with atherosclerosis progression via various mechanisms dependent on lipoprotein and also a pro-inflammatory state in plasma connected to circulating chemokines and cytokines." (PMID 37570897, 2023). "In recent years, PCSK9 has been linked to platelet activation during atherosclerosis disease progression." (PMID 35207479, 2022). "Next, experimental studies were performed in an attempt to find a potential mechanism underlying PCSK9 and platelet activation in the progression of atherosclerosis." (PMID 35207479, 2022).